NUSAP1 (nucleolar and spindle associated protein 1)
Diseases named in the same sentence as NUSAP1 in open-access papers (continued):
Sharing a sentence is not in itself a finding about the gene and the disease.
cervical carcinoma (18 papers, 2013 to 2025). A carcinoma arising from either the exocervical squamous epithelium or the endocervical glandular epithelium. "However, further prospective investigations are warranted to establish the diagnostic accuracy of NUSAP1 in cervical cancer." (PMID 32226503, 2020). "Moreover, immunohistochemical staining showed that NUSAP1 protein expression was positively and closely associated with nuclear β-catenin protein expression in the 233 paraffin-embedded cervical cancer tissues(P < 0.001)." (PMID 30678687, 2019). "Therefore, the present study analyzed the role of NUSAP1 in cervical cancer, and we assessed the association with the Wnt/β-catenin pathway in the progression and metastasis of cervical cancer." (PMID 30678687, 2019). "Likewise, NUSAP1 is a crucial mitotic regulator that binds to microtubules and mediates their attachment to chromosomes, ensuring the accurate distribution of genetic material to the two daughter cells, and it is associated with cervical cancer progression." (PMID 41516135, 2025). "Moreover, increased levels of NUSAP1 were associated with CSCs properties of cervical cancer." (PMID 30678687, 2019). "Conversely, contradictory results in cervical cancer showed that decreased NUSAP1 expression was correlated with poor prognosis." (PMID 39430250, 2024). "Recently, it was shown by several studies that NUSAP1 dysregulation has important oncogenic roles in various cancers, such as colorectal, prostate, breast, lung, and cervical cancer." (PMID 37304238, 2023). "For instance, in cervical cancer, NUSAP1 is shown to bound to the SUMO-E3 ligase Ran binding protein 2 (RanBP2) to induce the sumoylation of TCF4, thereby enhancing the Wnt/β signaling pathway and inducing tumor metastasis." (PMID 33927744, 2021). "Previously, it was demonstrated that NuSAP1 accelerates the metastasis of cervical carcinoma cells by activating Wnt/β-catenin signaling." (PMID 32651974, 2021). "Nucleolar and spindle associated protein 1(NUSAP1) was a gene from spindle associated pathway, and it was reported to promote the metastasis of cervical cancer by activating Wnt/β-catenin signaling." (PMID 33344075, 2020). "In the present study, GSEA was performed to investigate the potential signaling pathways of NUSAP1 in cervical cancer." (PMID 32226503, 2020). "In the present study, we showed that NUSAP1 was overexpressed in cervical cancer and correlated with unfavorable clinical outcome, especially via its critical role in promoting metastasis." (PMID 30678687, 2019). "Western blot assay and immunohistochemistry were used to determine the expression of NUSAP1 in 21 clinical fresh Cervical cancer tissues and 233 clinicopathologically characterized cervical cancer specimens." (PMID 30678687, 2019). "Prompted by these reports, we further examined CSCs and EMT in cervical cancer cells to detect the role of NUSAP1 in metastasis." (PMID 30678687, 2019). "Collectively, these results reveal that NUSAP1 promotes cervical cancer cells metastasis both in vitro and in vivo." (PMID 30678687, 2019). "To further explore the function of NUSAP1 in cervical cancer metastasis, we created stable NUSAP1-overexpressing and -knockdown cell lines using HeLa and SiHa cervical cancer cells." (PMID 30678687, 2019). "The biological roles of NUSAP1 in the metastasis of cervical cancer were investigated both in vitro by EMT, Side population analysis and Transwell assays and so on, and in vivo using a mouse 4w model of hematogenous metastasis and lymph node metastasis." (PMID 30678687, 2019). "We then evaluated the effect of NUSAP1 on cervical carcinoma metastasis in vivo by lung colonization models and popliteal lymph node metastasis model." (PMID 30678687, 2019). "The results demonstrated that NUSAP1 was upregulated in cervical cancer cells and tissues, correlated positively with metastasis and poor clinical outcome of patients." (PMID 30678687, 2019).
cervical carcinoma (continued). "In the present study, we revealed the oncogenic role and prognostic significance of NUSAP1 in cervical cancer, which agreed with the findings detailed above." (PMID 30678687, 2019). "The clinical significance of NUSAP1 was further assessed by immunohistochemistry (IHC) staining in 233 archived cervical cancer samples." (PMID 30678687, 2019). "Taken together, the results presented a novel mechanism by which NUSAP1 persistently activates Wnt/β-catenin signaling, demonstrating the significant role of NUSAP1 in the metastasis of cervical cancer cells." (PMID 30678687, 2019). "We analyzed the biological role of NUSAP1 in metastasis of cervical carcinoma by gene set enrichment analysis (GSEA) on the basis of mRNA expression data from TCGA of CESC samples." (PMID 30678687, 2019). "To explore the role of NUSAP1 in cervical cancer, we selected seven paired cervical carcinoma tissues and eight cervical cancer cell lines to detect its expression." (PMID 30678687, 2019). "To further explore the mechanism by which NUSAP1 promotes metastasis of cervical cancer cells, we analyzed publicly available gene expression array data for cervical cancer using GSEA." (PMID 30678687, 2019). "NuSAP1 has been demonstrated to activate Wnt/β-catenin signaling in cervical cancer cells." (PMID 32651974, 2021). "After combination of the expression pattern and survival analysis, eight upregulated hub gens (CCNB1, BUB1, CDK1, AURKB, KIF11, PBK and NUSAP1) stood out with dramatical upregulation in cervical cancer and were significantly correlated with good prognosis of cervical cancer (P < 0.05)." (PMID 33682613, 2021). "And with RT-PCR and western blot to NUSAP1 is upregulated in cervical cancer." (PMID 32226503, 2020). "Results of gene expression profiling of NUSAP1 suggest that it may play a critical role in cervical cancer." (PMID 32226503, 2020). "Importantly, co-therapy of conventional treatment and XAV-939 will provide a novel and effective treatment for NUSAP1-ovexpressed cervical cancer patients." (PMID 30678687, 2019). "Additionally, multivariate Cox regression analysis found that the NUSAP1 protein expression level and N classification were independent prognostic indicators for cervical cancer." (PMID 30678687, 2019). "Additionally, NUSAP1-induced cervical cancer cells metastasis and the cancer stem cell phenotype were abrogated with the Wnt/β-catenin signaling inhibitor XAV-939 treatment." (PMID 30678687, 2019). "We tested whether SUMOylation E3 ligase (RanBP2) co-IPed with endogenous NUSAP1 in cervical cancer cells." (PMID 30678687, 2019). "Collectively, these data suggested that the Wnt/β-catenin pathway is required for NUSAP1-mediated metastasis in cervical cancer cells and NUSAP1 enhanced nuclear β-catenin protein expression and then evoked Wnt/β-catenin signaling which resulted in promotion of metastasis in cervical cancer samples." (PMID 30678687, 2019). "Microarray analysis (The Cancer Genome Atlas (TCGA) (Cervical squamous cell carcinoma and endocervical adenocarcinoma (CESC) TCGA data), GSE7803 and GSE9750) revealed that NUSAP1 was upregulated in cervical cancer samples compared with that in normal cervix tissues." (PMID 30678687, 2019). "Taken together, these results showed that NUSAP1 promotes EMT in cervical cancer cells." (PMID 30678687, 2019). "To assess whether NUSAP1 promotes the CSC properties of cervical cancer cells, we first analyzed the GSEA based on mRNA expression data from TCGA of CESC samples.." (PMID 30678687, 2019). "Moreover, we also performed tumor sphere formation assays to detect the effect of NUSAP1 on the self-renewal of cervical cancer cells." (PMID 30678687, 2019). "The results showed that NUSAP1 was upregulated in cervical cancer cell lines, and NUSAP1 could serve as an independent prognostic indicator for unfavorable clinical outcomes." (PMID 30678687, 2019).
cervical carcinoma (continued). "Therefore, our study revealed a potential mechanism for Wnt/β-catenin pathway activation, and suggested NUSAP1 as a novel therapeutic target in patients with cervical carcinoma." (PMID 30678687, 2019). "Thus, our study provides evidence for the clinical and biological significance of NUSAP1 in cervical cancer." (PMID 30678687, 2019). "In this work we identified 6 genes (PRC1, CCNB2, SYCP2 CDKN3, NUSAP1, and CDC20) associated with invasive cervical cancer that could be used either as markers for diagnosis or as therapeutic targets." (PMID 23405241, 2013). "Furthermore, the extraction of the patient follow-up data from the Cancer Genome Atlas (TCGA) database might help in exploring the prognostic value of NUSAP1 in cervical cancer and its correlations with other major clinical factors." (PMID 32226503, 2020). "However, the association between NUSAP1 expression and prognosis and its biological functions and correlation with other predominant clinical factors of cervical cancer have not been investigated." (PMID 32226503, 2020). "The results of these studies will not only contribute to our understanding of NUSAP1 to cervical cancer metastasis but will also lead to the characterization of specific tumor patients’ groups with NUSAP1 overexpression who may benefit from co-therapy of traditional treatment and XAV-939." (PMID 30678687, 2019). "Moreover, NUSAP1 could be used to predict postoperative metastasis and recurrence in patients with cervical cancer, and a Wnt/β-catenin pathway inhibitorXAV-939 may serve as a potential tailored treatment for NUSAP1-ovexpressed cervical cancer patients." (PMID 30678687, 2019). "Consistently, NUSAP1 increased the proportion of side population phenotypes cells, which is regarded as a characteristic feature of CSCs, indicating that NUSAP1 may promote the stemness of cervical cancer cells." (PMID 30678687, 2019). "Of the top 10 ranked upregulated genes, 2 have not been previously reported as associated with cervical cancer (NUSAP1, and CDKN3), while the other 8 have been associated with cervical cancer either scantly (SYCP2, PRC1, CCNB2 and CDC20) or widely (MKI67, CDKN2A, CDC2, and PCNA)." (PMID 23405241, 2013). "For instance, decreased expression of NUSAP1 and TP73 predicts poor overall survival in cervical cancer." (PMID 35832191, 2022). "In the present study, we showed that high expression of NUSAP1 induces an EMT-like phenotypic transition and metastasis in cervical cancer cells." (PMID 30678687, 2019). "However, the function of NUSAP1 in cervical cancer remains unknown." (PMID 30678687, 2019). "Although the precise mechanisms of NUSAP1-induced EMT requires further investigation, we believe that high expression of NUSAP1 promotes EMT and induces metastasis in cervical cancer cells at least partly depending on activated Wnt/β-catenin signaling." (PMID 30678687, 2019). "Mechanistically, upregulation of NUSAP1 induced SUMOylation of TCF4 via interacting with SUMO E3 ligase Ran-binding protein 2 (RanBP2) and hyperactivated Wnt/β-catenin signaling in cervical cancer cells." (PMID 30678687, 2019). "NUSAP1 overexpression induced SUMOylation of TCF4 via binding NPC protein, RanBP2, is involved in the process of cervical cancer metastasis and progression." (PMID 30678687, 2019). "Then, the top 40 hub genes were conducted to evaluate the expression and prognostic values of cervical cancer and 7 upregulated (BUB1, CCNB1, CDK1, AURKB, KIF11, PBK, NUSAP1) and 1 downregulated (ESR1) hub genes were selected to have significant values as biomarkers." (PMID 33682613, 2021). "MTT assay shows that overexpression of NUSAP1 or knockdown of NUSAP1 did not significantly affect proliferation rates of cervical cancer Hela and Siha cell lines." (PMID 30678687, 2019). "Moreover, NUSAP1-induced invasion, EMT, and stemness in cervical cancer cells were repressed by the XAV939 or β-catenin siRNA treatments." (PMID 30678687, 2019).
cervical carcinoma (continued). "Our results also reveal that NUSAP1 increased the nuclear import of the TCF4 and β-catenin and their transcriptional activity via interacting with RanBP2 protein, and then enhanced CSCs properties and EMT processes in cervical cancer." (PMID 30678687, 2019). "Moreover, NUSAP1 induced SUMOylation of TCF4 via interacting with SUMO E3 ligase Ran-binding protein 2 (RanBP2) and potently activated the Wnt/β-catenin signaling pathway, thus contributing to the metastatic and CSC-likeproperties of cervical cancer cells." (PMID 30678687, 2019). "Therefore, our data suggested that NUSAP1 might represent as a new regulator of EMT and may also represent a potential therapeutic target in cervical cancer." (PMID 30678687, 2019). "Studies also showed that the over-expression of NUSAP1 stimulated sumoylation of TCF4 via interacting with SUMO E3 ligase Ran-binding protein 2 and hyperactivated Wnt/β-caternin signaling to induce cancer stem cell properties and EMT, and finally promoted the metastasis of cervical cancer." (PMID 31729978, 2019). "Our results demonstrate thatNUSAP1 upregulation contributes to metastasis of cervical cancer by promoting CSC properties and EMT via Wnt/β-catenin signaling and XAV-939 might serve as a potential tailored therapeutic option for patients with NUSAP1-ovexpressed cervical cancer." (PMID 30678687, 2019).
glioblastoma (16 papers, 2013 to 2025). The most malignant astrocytic tumor (WHO grade IV). "Another marker, NUSAP1, which is a microtubule-associated protein involved in mitosis, is also known to participate in cell proliferation, apoptosis, and repairing DNA damage in glioblastoma multiforme cells." (PMID 36199789, 2022). "The analysis indicated that glioblastoma patients exhibiting genomic alterations in PCNA clamp-associated factor (PCLAF), RRM2, nucleolar and spindle-associated protein 1 (NUSAP1), and KIF23 displayed reduced overall survival rates, as shown in Fig.." (PMID 39248068, 2025). "Silencing NUSAP1 expression inhibits the proliferation, migration, and invasion of colorectal and glioblastoma cells by downregulating DNMT1 or TOP2A." (PMID 40393971, 2025). "LINC01393 promotes the occurrence and development of Glioblastoma by up-regulating NUSAP1 as a ceRNA of miRNA-128-3p and activating the NF-κB pathway." (PMID 40535133, 2025). "Studies showed that NUSAP1 knockdown reduces the sumoylation level of ATR and cause DNA damage in glioblastoma multiforme cells." (PMID 35739489, 2022). "High expression of NUSAP1 can be used as a prognostic biomarker for glioblastoma multiforme, pancreatic cancer, and colon cancer." (PMID 35487972, 2022). "We first analyzed the expression levels of NUSAP1 in astrocytoma, including anaplastic astrocytoma (n = 19) and glioblastoma (n = 81), using data deposited in the Oncomine database." (PMID 28899410, 2017). "Recently, overexpression of NUSAP1 has been found in various human cancers by array analysis, including glioblastomas, hepatocellular carcinomas, pancreatic adenocarcinoma." (PMID 23756599, 2013). "NUSAP1 is overexpressed in hepatocellular carcinoma and glioblastoma." (PMID 34094915, 2021). "Nucleolar and spindle-associated protein 1 (NUSAP1) is a potential molecular marker and intervention target for glioblastoma (GBM)." (PMID 36982952, 2023). "Research has demonstrated that NUSAP1 stabilizes ATR protein expression, promoting glioblastoma proliferation and resistance to temozolomide." (PMID 40393971, 2025). "Similar to the findings in benign brain tumor, NUSAP1 was reported to be overexpressed in grade III versus grade I meningiomas, and in glioblastoma multiforme." (PMID 28899410, 2017).
hepatocellular carcinoma (16 papers, 2013 to 2025). A malignant tumor that arises from hepatocytes. "Similarly, inhibition of NUSAP1 or ATAD2 caused apoptosis in human colorectal cancer or hepatocellular carcinoma, respectively." (PMID 30560474, 2019). "For instance, in liver cancer patients, decreased expression of miR-193a-5p, miR-122, and miR-18b results in elevated NUSAP1 levels, which in turn promotes the proliferation of hepatocellular carcinoma cells." (PMID 40535133, 2025). "Extensive research has demonstrated that NUSAP1 is overexpressed in various malignant tumors such as glioma, hepatocellular carcinoma, gastric cancer, lung cancer, prostate cancer, breast cancer, and bladder cancer." (PMID 40535133, 2025). "NUSAP1 is also regulated by hsa-miR-18b-5p and affects the proliferation of hepatocellular carcinoma." (PMID 35710427, 2022). "NUSAP1 knockdown induced G0/G1 phase arrest in gastric cancer (GC) and hepatocellular carcinoma (HC) cells." (PMID 34782617, 2021). "Overexpression of NUSAP1 has been observed in a variety of malignant tumors such as metastatic breast cancer, hepatocellular carcinomas, and pancreatic adenocarcinoma." (PMID 26554377, 2015). "A substantial body of research has employed diverse bioinformatics approaches to identify oncogenic genes, revealing that NUSAP1 is a hub gene frequently observed in various digestive system tumors, including hepatocellular carcinoma, gastric cancer, colorectal cancer, and pancreatic cancer." (PMID 40535133, 2025). "The immune infiltration analysis of hepatocellular carcinoma showed that NUSAP1 might regulate the immune microenvironment by influencing CD4+ T cells." (PMID 37752167, 2023). "Moreover, NUSAP1 expression has a significant role in the prediction of clinical outcome in hepatocellular carcinoma, in which NUSAP1regulates cellular proliferation, migration, and growth." (PMID 30678687, 2019). "Therefore, we believe that the highly expressed NUSAP1 may be temporarily used as a hepatocellular carcinoma Signs of disease." (PMID 33986994, 2021). "NUSAP1 can bind to c-Myc and HIF-1α, not only directly enhancing glycolysis and lactate production in hepatocellular carcinoma (HCC) cells but also increasing NUSAP1 lactylation levels through a positive feedback loop, further promoting the proliferation of HCC cells." (PMID 40860191, 2025).